CD36 (CD36 molecule (CD36 blood group))
Diseases named in the same sentence as CD36 in open-access papers (continued):
Sharing a sentence is not in itself a finding about the gene and the disease.
malaria (continued). "CD36 contributes to macrophage-mediated clearance of Plasmodium falciparum parasitized erythrocytes, and CD36 deficiency is associated with a dysregulated cytokine response and increased mortality in experimental animal models of severe malaria." (PMID 20950462, 2010). "The higher numbers of isolates causing both severe (89%) and uncomplicated malaria (78%) could bind to CD36." (PMID 19650937, 2009). "Additionally, polymorphisms in CD36, and CD36 deficiency, exist as natural variants in malaria endemic regions, including Asia and Africa." (PMID 18483551, 2008). "Thus, since CD36 presents a dual role in the pathogenesis of malaria, its higher expression in PbNK65-infected groups might indicate susceptibility to severe malaria in this experimental model." (PMID 39300444, 2024). "ICAM-1 and CD36 are strong candidate receptors for interactions with iRBC containing mature Plasmodium parasites within the microvasculature at the time of sequestration, in both human infections and rodent model infections, and for the associated development of severe malaria pathologies." (PMID 28468674, 2017). "Whereas most group B and C PfEMP1 proteins appear to be under selection to bind CD36 and tend to be associated with uncomplicated and asymptomatic malaria, groups A and B/A are often expressed in young children with limited malaria immunity and in those with SM." (PMID 27835682, 2016). "Recently, it has been suggested that CD36 may protect against anaemia caused by malaria." (PMID 25360558, 2014). "As with HbS in malaria, CD36 polymorphisms may exhibit a heterozygous advantage." (PMID 22909232, 2012). "If CD36 mutations do confer susceptibility to cerebral malaria, these mutations may be maintained in human populations through selection pressure of another prevalent infection other than malaria, or perhaps even by resistance to malaria-associated ALI." (PMID 18483551, 2008). "It concludes how the PfEMP1 family enables the parasite to evade the immune system through antigenic variation, allowing it to adhere to host receptors such as CD36, ICAM-1, PECAM-1, and EPCR, which are associated with severe malaria." (PMID 40523953, 2025). "Significantly, individuals from malaria-endemic regions produce PfEMP1-specific antibodies that can engage Fc receptors and also express the CD36 scavenger receptor on the monocyte surface, which can directly bind certain variants of PfEMP121,22." (PMID 38316918, 2024). "CD36 is a scavenger receptor on monocytes and macrophages that serves several important protective roles, such as the destruction of malaria-infected RBCs." (PMID 38988513, 2024). "CD36 is an essential molecule in the pathogenesis of malaria, expressed in platelets, mature monocytes, macrophages, and erythroid precursors." (PMID 39300444, 2024). "The interactions between malaria parasites and human CD36 have been well documented, especially in the pathogenesis of P. falciparum infection." (PMID 37981686, 2023). "Dual ICAM-1-EPCR binding IE were more common in patients with cerebral malaria than in patients with uncomplicated malaria, whereas CD36 binders were more frequently found in patients with uncomplicated malaria." (PMID 36419237, 2023). "Human cluster of differentiation 36 (CD36) participates in malaria pathophysiology with either protective or pathological roles." (PMID 37981686, 2023). "As this effect is particularly evident at low levels of parasitemia, the role of CD36 for malaria immunity appears to take place early during infection and to promote the development of protective immunity against malaria." (PMID 36557610, 2022). "Further studies also showed that parasite cytoadhesion to CD36 correlates with the development of mild malaria." (PMID 36557610, 2022). "Schizonts of malaria parasites bind to vascular endothelial cells by interacting with the endothelial receptor CD36 and sequestration-related proteins, such as SBP1 and MAHRP1a." (PMID 34644348, 2021).
malaria (continued). "CD36 plays a dual role in malaria: its expression in phagocytes induced at early stage of infection has an important effect on parasites clearance; whereas that in endothelial cells mediates parasite sequestration in microvasculature of organs." (PMID 34025654, 2021). "During the malaria-induced inflammatory processes, the treatment of macrophages with NRF2 inducers enhances the CD36 expression and CD36-mediated Plasmodium phagocytosis and thus the control of severe malaria through parasite clearance." (PMID 33898331, 2021). "Several data have been generated in the context of malaria disease, in which phagocytosis of Plasmodium falciparum-infected erythrocytes is mediated by macrophages expressing the receptor CD36." (PMID 34279684, 2021). "Overall, it is unlikely that CD36 is a clinically significant rosetting receptor or a useful therapeutic target in severe malaria." (PMID 31455446, 2020). "Except for CD36, the expression of the other platelet markers in malaria cases differed significantly from the controls." (PMID 32268918, 2020). "Very different pathologies, such as cardiovascular disease, malaria, and tumor metastasis, share a mechanism involving the membrane glycoprotein CD36." (PMID 31379931, 2019). "And, when the binding capacity to CD36, ICAM‐1 or EPCR was investigated, adhesion to EPCR and ICAM‐1 was more common in cerebral malaria‐causing parasites than in uncomplicated malaria‐causing parasites." (PMID 30804082, 2019). "We revisited genetic evidence provided by inflammatory response genes that have been repeatedly associated to malaria, namely TNF, NOS2, IFNAR1, HMOX1, TLRs, CD36, and CD40LG." (PMID 31417551, 2019). "We found that all Bubi individuals possessed the malaria-resistant allele of the ACKR1 and CD36 genes, in addition to certain variations in other genes such as G6PD, ATP2B4, GRK5, and IL-10." (PMID 30841922, 2019). "We first confirmed previous reports showing that CD36 acts as a phagocytic receptor in the internalization of malaria parasites and that TLR4 is a receptor involved in the phagocytosis of E. coli by macrophages." (PMID 30158654, 2018). "It has been reported that CD36 is a receptor involved in the phagocytosis of malaria parasites and TLR4 in the phagocytosis of E. coli." (PMID 30158654, 2018). "We observed that the percentage of malaria parasites phagocytosed by CD36−/− macrophages is markedly decreased, compared to wild-type macrophages." (PMID 30158654, 2018). "To confirm that CD36 plays a role in the increase in phagocytosis observed upon Rab14 silencing, we cultured macrophages treated with siRNA for Rab14 with erythrocytes infected with malaria parasites in the presence of CD36 blocking antibody." (PMID 30158654, 2018). "To confirm the requirement for the CD36 receptor in the phagocytosis of malaria parasites, we used macrophages pre-treated with a CD36 blocking antibody." (PMID 30158654, 2018). "We confirmed that CD36 is a receptor involved in the phagocytosis of the malaria parasite P. berghei and found that when Rab14 is silenced the levels of surface CD36 increase, which can explain the increase in phagocytosis we have observed previously." (PMID 30158654, 2018). "PPARγ agonists have been proposed as malaria therapeutics and can increase CD36-mediated phagocytosis of iRBCs while reducing malaria-induced TNFα secretion." (PMID 29891920, 2018). "The demonstration that ICAM-1-binding parasites have diverged in EPCR and CD36 coreceptor adhesion traits has particular significance for efforts to correlate malaria clinical syndromes to specific parasite binding types." (PMID 27406562, 2016). "Targeting of the CD36 scavenger receptor by the malaria parasite effector PfEMP1 prevents splenic clearance of infected erythrocytes." (PMID 27667267, 2016). "The exact effects of increased CD36 affinity in determining resistance to malaria in SAO remain to be determined." (PMID 26215182, 2015).
malaria (continued). "On endothelial cells, CD36 is known for its role as a negative regulator of angiogenesis and has also been identified as a sequestration receptor for Pf-iE during malaria, although the main sequestration receptor during PAM is chondroitin sulfate A (CSA)." (PMID 26385579, 2015). "Adhesion to CD36 is seen for IE from severe or uncomplicated malaria patients except isolates from pregnancy-associated malaria, although in some studies it has been associated with uncomplicated malaria isolates." (PMID 25360558, 2014). "Although P. falciparum does not infect mice, mouse and human CD36 closely resemble one another (90% identity in their amino acid sequences), and that mouse CD36 mediates the sequestration of rodent malaria parasites in vivo." (PMID 24204889, 2013). "In conclusion, in this study we demonstrate that CD36 plays a significant role in the uptake of malaria parasite IRBCs." (PMID 24204889, 2013). "The results show that in early malaria, selected immune response-related genes were up-regulated including α β and γ interferon-related genes, as well as genes of IL-15, CD36, chemokines (CXCL10, CCL2, S100A8/9, CXCL9, and CXCL11), TRAIL and IgG Fc receptors." (PMID 24188121, 2013). "The scavenger receptor CD36 plays important roles in malaria, including the sequestration of parasite-infected erythrocytes in microvascular capillaries, control of parasitemia through phagocytic clearance by macrophages, and immunity." (PMID 24204889, 2013). "The reason for the discrepancy in the role of CD36 in malaria is unclear and further studies are required." (PMID 23967200, 2013). "In contrast, malaria-infected CD36−/− mice had near normal fluid conductance but a similar reduction in σalb." (PMID 23967147, 2013). "Our finding that human pDCs are substantially less phagocytic than mDCs, even though pDCs express substantial levels of CD36 on their surface, appears to have an important implication from the point of view of malaria immunity." (PMID 24204889, 2013). "Here, we show that the CD36-mediated uptake of IRBCs plays an important role in the pro-inflammatory cytokine responses to malaria by DCs and in the DC-dependent activation of NK and T cells and cytokine production." (PMID 24204889, 2013). "Although the role of CD36 in the parasite sequestration and clearance has been extensively studied, how and to what extent CD36 contributes to malaria immunity remains poorly understood." (PMID 24204889, 2013). "Total Fyn protein levels were unchanged in malaria-infected WT lungs compared to control, but significantly increased in PbA-infected CD36−/− lungs compared to both control lungs and infected WT lungs." (PMID 23967147, 2013). "The in vitro data in MLMVEC monolayers and the in vivo results in malaria-infected lungs implicate Fyn kinase as a critical downstream mediator of CD36-dependent lung endothelial dysfunction." (PMID 23967147, 2013). "In murine models of human malaria, CD36 on vascular endothelial cells is the major binding partner for iRBCs." (PMID 23967147, 2013). "In conclusion, this study is the first to show the critical roles that CD36 and the tyrosine kinase Fyn play as mediators of the increased pulmonary endothelial permeability found in malaria-infected mice." (PMID 23967147, 2013). "CD36 also controls parasitemia through phagocytic clearance of IRBCs by macrophages and protects mice against malaria." (PMID 24204889, 2013). "On the other hand, the contribution of CD36 toward the production of pro-inflammatory cytokines is essential for the efficient development of protective immunity to malaria." (PMID 24204889, 2013). "In contrast, the lungs from PbA-infected CD36−/− mice had markedly attenuated changes in Kf and Ff indicating near-complete protection from malaria-induced paracellular hyperpermeability." (PMID 23967147, 2013).
malaria (continued). "In striking contrast, the lungs of malaria-infected CD36−/− animals demonstrated significantly decreased water conductance when compared to WT mice, consistent with the observed lack of histological evidence of pulmonary edema after malaria challenge." (PMID 23967147, 2013). "In the case of malaria, CD36 functions as a main receptor for the adherence of IRBCs and consequent sequestration of parasites in the microvascular endothelia." (PMID 24204889, 2013). "The importance of CD36-mediated innate control of acute blood-stage malaria was demonstrated in vivo, in a murine model of hyperparasitemia (P. chabaudi AS infection)." (PMID 21772838, 2012). "PfEMP1 proteins belonging to group A (previously implicated in severe malaria), groups B, B/C, and C (that typically bind the glycoprotein CD36), and VAR2CSA (previously implicated in pregnancy malaria) were included in the array as single or tandem domains." (PMID 22295123, 2012). "The use of PPARγ agonists to modulate immune responses to malaria was initially motivated by reports demonstrating that PPARγ regulates CD36 transcription and that PPARγ agonists have anti-inflammatory properties." (PMID 21772838, 2012). "9-cis-retinoic acid is a metabolite of vitamin A and an agonist of PPARγ (via RXR ligation), and like rosiglitazone, has been shown to enhance CD36-mediated PE uptake and reduce malaria-induced TNF production in vitro." (PMID 21772838, 2012). "Here, we highlight recent advances in our current understanding of the biological actions of PPARγ on CD36 and malaria clearance from the hosts." (PMID 22287954, 2012). "CD36-null mice experience more severe and fatal malaria when challenged with Plasmodium chabaudi chabaudi as compared with wild-type mice." (PMID 22287954, 2012). "CD36 serves as a ligand receptor of thrombospondin, long chain fatty acids, oxidized low density lipoproteins (LDLs) and malaria-infected erythrocytes." (PMID 24970143, 2012). "Recent data provide evidence that rosiglitazone PPARγ ligand can in vitro and in vivo improves the outcome of experimental malaria in mice, enhancing CD36-mediated PEs phagocytic processes and limiting parasite-induced inflammatory processes." (PMID 21949655, 2011). "P. falciparum isolates from children with UM have significantly higher levels of adhesion to CD36, under static conditions, than isolates from children with severe disease (CM, Severe Malaria-other and SMA)." (PMID 21390226, 2011). "The findings presented here provide a platform from which to focus efforts on blocking or reversing ICAM-1-mediated adhesion to reduce cerebral malaria as well as a reconsideration of anti-CD36 strategies for controlling severe malaria." (PMID 21390226, 2011). "In addition, children homozyogous for a mutation change of T to G in the CD36 gene at nucleotide position 188 in exon 10 are protected against severe malarial anaemia and children carrying the sickle cell trait, HbS are protected against all forms of malaria disease." (PMID 21390226, 2011). "We have shown for the first time in African children that parasites isolated from children with UM bind to CD36 at higher densities than parasites from children with severe malaria." (PMID 21390226, 2011). "This current study assessed the adhesion of P. falciparum infected erythrocytes under flow (ICAM-1) and static (ICAM-1 and CD36) conditions from children with different clinical syndromes of malaria." (PMID 21390226, 2011). "The conventional way to promote CD36 expression through PPARγ nuclear receptor is inefficient under malaria inflammatory processes." (PMID 21949655, 2011). "We demonstrate here that malaria-induced inflammation down regulates CD36 expression on macrophages and favors the worsening of malaria infection." (PMID 21949655, 2011). "The rodent malaria strain P. chabaudi has been used to study malaria sequestration in mice, and P. chabaudi AS-infected red blood cells adhered to purified CD36 in vitro." (PMID 19680452, 2009).
malaria (continued). "In malaria, CD36 ectodomain phosphorylation at Thr92 can regulate pRBC adhesion to CD36 and to human dermal microvascular endothelial cells (HDMECs) under flow conditions, and is regulated by a Src family kinase- and alkaline phosphatase dependent mechanism." (PMID 19450262, 2009). "The antiretroviral protease inhibitors ritonavir and saquinavir affect CD36-mediated cytoadherence, thought to play a role in cerebral malaria and other end-organ damage in severe malaria." (PMID 19680452, 2009). "In summary, parasite burden and CD36-mediated sequestration in the lung are primary determinants of ALI in experimental murine malaria." (PMID 18483551, 2008). "Therefore, while CD36 remains a gene of interest in malaria pathophysiology, its evolutionary trajectory appears to be influenced by a complex interplay of environmental factors beyond malaria alone." (PMID 40993672, 2025). "In addition, C1INH was described to suppress malaria parasite invasion of host erythrocytes and cytoadhesion by binding to parasite glycosylphosphatidylinositol and the host cell receptors CD36 and chondroitin sulfate A." (PMID 40243929, 2025). "However, CD36 also mediates phagocytic clearance of IEs by macrophages and dendritic cells, highlighting its dual role in malaria immunity (Patel SN." (PMID 41450567, 2025). "Schizonts of malaria parasites bind to vascular endothelial cells through interactions between the endothelial receptor CD36 and sequestration-related proteins such as skeleton binding protein 1 (SBP1) and membrane associated histidine-rich protein 1a (MAHRP1a)." (PMID 38195464, 2024). "Adhesion to CD36 has been frequently associated with parasites causing uncomplicated, rather than severe malaria." (PMID 36419237, 2023). "To determine whether ABO genotype might influence malaria susceptibility via these mechanisms, we conducted in vitro experiments examining cytoadhesion to ICAM-1 and CD36 and PfEMP1 display in relation to infected RBC ABO genotype." (PMID 37708213, 2023). "Furthermore, RXR agonists, which upregulate CD36 expression through direct promoter interactions, were shown to induce an increase in CD36-mediated phagocytosis and a decrease in malaria-induced TNF-α secretion by human monocytes and macrophages." (PMID 36674699, 2023). "Furthermore, this interaction was specific at the molecular level in in vitro analysis, as MTRAP proteins from other human-infecting malaria parasites were unable to bind to CD36." (PMID 37981686, 2023). "A heterozygous genotype (TG) of CD36 was protective against severe malaria in India." (PMID 34698295, 2021). "Thus, we presume CD36 is delivered to malaria parasites from platelets by exosomes, which enables parasites to steal HDL for cholesterol supply." (PMID 34858976, 2021). "Maybe parasite binding to CD36 is specifically enhanced in adult severe malaria cases compared to children, which is interesting due to their different disease symptomatology." (PMID 33908865, 2021). "Intriguingly, while CD36 deficiency is fairly common in African populations, large-scale genetic studies have shown that CD36 polymorphisms do not influence severe malaria risk." (PMID 31455446, 2020). "Furthermore, parasite isolates from cerebral malaria patients more frequently exhibited binding to both ICAM‐1 and EPCR, whereas binding to CD36 was more frequent in uncomplicated malaria than cerebral malaria patients." (PMID 30804082, 2019). "Similarly, CD36, an important marker for malaria, was higher in treated cells compared to untreated ones." (PMID 31852507, 2019). "Individuals homozygous for this mutation which ablates CD36 protein surface expression showed reduced antibody response to malaria blood stage antigens suggesting that CD36 takes part in the initial steps of the adaptive immune response possibly by mediating phagocytosis of infected red blood cells." (PMID 31417551, 2019).